PLK2 (polo like kinase 2)
Description:
Tumor suppressor serine/threonine-protein kinase involved in synaptic plasticity, centriole duplication and G1/S phase transition. Polo-like kinases act by binding and phosphorylating proteins that are already phosphorylated on a specific motif recognized by the POLO box domains. Plays a key role in synaptic plasticity and memory by regulating the Ras and Rap protein signaling: required for overactivity-dependent spine remodeling by phosphorylating the Ras activator RASGRF1 and the Rap inhibitor SIPA1L1 leading to their degradation by the proteasome. Also regulates synaptic plasticity independently of kinase activity, via its interaction with NSF that disrupts the interaction between NSF and the GRIA2 subunit of AMPARs, leading to a rapid rundown of AMPAR-mediated current that occludes long term depression. Required for procentriole formation and centriole duplication by phosphorylating CPAP and NPM1, respectively.
Synonyms: hPlk2; hSNK; SNK
Tractability: Small molecule: a structure with a bound ligand is known; a high-quality ligand is known; it belongs to a druggable protein family. PROTAC: ubiquitination databases record sites on it; a small molecule that binds it is known.
Target class: Protein Kinase; Kinase; Other protein kinase group; Other protein kinase PLK2; Other protein kinase PLK family; Enzyme
Chemical probes: BI 2536 (high quality), PD134165, PD134166, PD134168
Gene: Protein-coding gene on chromosome 5 (58,453,982 to 58,460,139, reverse strand). Ensembl gene ENSG00000145632.
Subcellular location: Cytoplasm, cytoskeleton, microtubule organizing center, centrosome, centriole; Cell projection, dendrite
Subcellular location (Human Protein Atlas): Cytosol; Mitochondria; Nucleoplasm
Pathways (Reactome):
Gene expression (Transcription): NPAS4 regulates expression of target genes
Disease: CD163 mediating an anti-inflammatory response
Gene Ontology:
Molecular function: ATP-dependent protein binding; protein binding; protein serine/threonine kinase activity; ATP binding; protein kinase activity; protein serine kinase activity
Biological process: G1/S transition of mitotic cell cycle; mitotic spindle organization; positive regulation of autophagy; positive regulation of canonical NF-kappaB signal transduction; positive regulation of protein catabolic process; protein phosphorylation; regulation of centriole replication; long-term synaptic depression; long-term synaptic potentiation; memory; negative regulation of apoptotic process; negative regulation of inflammatory response to antigenic stimulus; Rap protein signal transduction; Ras protein signal transduction; regulation of synaptic plasticity; negative regulation of angiogenesis; negative regulation of apoptotic process in bone marrow cell; negative regulation of cellular senescence; positive regulation of cell migration involved in sprouting angiogenesis; regulation of cell cycle process
Cellular component: centriole; centrosome; cytoplasm; cytosol; dendrite; kinetochore; nucleus; spindle pole; chromatin
Genetic constraint (gnomAD): Loss-of-function variants: 17 observed, 54.1 expected, observed/expected ratio (o/e) 0.31, 90% interval 0.21 to 0.47. The upper end of that interval is the gene's LOEUF score, 0.47, which puts it in group 2 of 6, group 1 being the genes least tolerant of losing a copy. Missense variants: 479 observed, 696.65 expected, observed/expected ratio (o/e) 0.69, 90% interval 0.64 to 0.74. Synonymous variants: 286 observed, 257.47 expected, observed/expected ratio (o/e) 1.11, 90% interval 1.01 to 1.23.
Homologues: Orthologues: chimpanzee PLK2 (100% identical), macaque PLK2 (99% identical), guinea pig PLK2 (98% identical), dog PLK2 (98% identical), pig PLK2 (98% identical), rat Plk2 (97% identical), mouse Plk2 (97% identical), rabbit PLK2 (95% identical), tropical clawed frog plk2 (76% identical), zebrafish plk2a (73% identical), zebrafish plk2b (68% identical). Paralogues in human: PLK3 (47% identical), PLK1 (34% identical), PLK4 (25% identical), PLK5 (16% identical).
Diseases named in the same sentence as PLK2 in open-access papers:
PLK2 is named in the same sentence as 97 diseases in open-access papers, as found by Europe PMC text mining. Sharing a sentence is not in itself a finding about the gene and the disease. The quoted sentences say what the papers report.
ovarian carcinoma (14 papers, 2012 to 2026). A malignant neoplasm originating from the surface ovarian epithelium. "In epithelial ovarian cancer, CpG island methylation causes PLK2 downregulation, which is related to paclitaxel and platinum tolerance and postoperative recurrence." (PMID 38339228, 2024). "Critical involvement of upregulated PLK2 in resistance development is underlined by a transcriptome monitoring in isogenic ovarian cancer cells with gradually changing resistance." (PMID 34065956, 2021). "High PLK2 rexpression has been confirmed in osteosarcomas, and down-regulated PLK2 could be associated with chemotherapy resistance in epithelial ovarian cancer." (PMID 31763067, 2019). "Lower expression of BCL2L1 and PLK2 displayed favorable outcomes independently, and when combined indicating a role of BCL2L1 and PLK2 in ovarian cancer." (PMID 36733702, 2023). "Reportedly, PLK2 expression was positively correlated to paclitaxel resistance resulting from its anti-proliferative effects during mitosis in ovarian cancer cell line A2780 and promoting tumor cell viability." (PMID 35898867, 2022). "The ERK1/2/Plk2 signaling axis mediates the inhibitory effect of anlotinib on the proliferation and migration of ovarian cancer cell lines." (PMID 36558006, 2022). "For example, high expression of tubulin beta 3 class III (TUBB3) and low expression of salt inducible kinase (SIK2), polo-like kinase 2 (PLK2) or spleen tyrosine kinase (SYK) restore the paclitaxel sensitivity of ovarian cancer cells." (PMID 35477477, 2022). "This was confirmed in a follow-up study and is in accordance with significant downregulation of the Plk2 gene identified in chemo resistant ovarian cancer via oligonucleotid microarrays." (PMID 34065956, 2021). "The role of PLK2 in ovarian cancer is of special interest for this review and will be discussed further below." (PMID 34065956, 2021). "Silencing of PLK2 dramatically sensitizes an ovarian cancer cell line to anti-microtubule agents leading to apoptosis during mitosis." (PMID 34065956, 2021). "The methylation status of the PLK2 CpG island varies with sensitivity to paclitaxel and platinum in ovarian cancer cell lines." (PMID 22289679, 2012). "Plk2 is epigenetically inactivated in malignant lymphomas, and silencing of Plk2 enhances tumor growth in non–small cell lung carcinoma, ovarian carcinoma, and gastric cancer." (PMID 35842499, 2023). "The Gene Expression Omnibus (GEO) dataset GSE15372 was used to identify PLK2 as a differentially expressed gene (DEG) for drug resistance in ovarian cancer, and Western blotting and qRT-PCR showed that PLK2 expression was significantly lower in drug-resistant ovarian cells." (PMID 36558006, 2022). "To investigate whether anlotinib inhibited the proliferation of cisplatin-resistant ovarian cancer cells by inducing the expression of PLK2, we constructed si-PLK2 cells." (PMID 36558006, 2022). "And in epithelial ovarian cancer (EOC), CpG island methylation caused PLK2 downregulation was related to paclitaxel and platinum tolerance and postoperative recurrence, being confirmed by knockdown and overexpression experiments and indicating the relevance to G2-M arrest." (PMID 35898867, 2022). "PLK2 methylation in ovarian cancer observed to correlate with patients treated with chemotherapy." (PMID 35256538, 2022). "Therefore, the authors proposed the PLK2 status as a clinically important marker of chemosensitivity in the ovarian cancer treatment." (PMID 33287223, 2020). "In the present study, we explored the expression of PLK2 in cisplatin-resistant ovarian cancer cells treated with or without anlotinib." (PMID 36558006, 2022).
colorectal cancer (12 papers, 2020 to 2026). A primary or metastatic malignant neoplasm that affects the colon or rectum. "PLK2 and PLK3 have been proposed to act as tumor suppressor proteins, and the loss of PLK2 was identified as a common change found in colorectal carcinomas, lending support to PLK2 being identified as a tumor suppressor." (PMID 35053604, 2022). "In contrast, another study suggested that PLK2 was a tumor suppressor and its loss was more common in colorectal carcinoma than adenomas." (PMID 35156101, 2021). "In colorectal cancer (CRC), elevated PLK2 expressionis associated with chemoresistance and poor patient prognosis, makingit a compelling target for therapeutic intervention." (PMID 41405409, 2026). "Among them, PLK2 was found to induce the growth and proliferation of colorectal cancer cells, whereas TIG1 prevents this process." (PMID 39726813, 2024). "In contrast, Plk2 is also reported as an oncogenic factor based on its overexpression and tumor-promoting effects in colorectal cancer, bladder cancer, and pancreatic cancer." (PMID 35842499, 2023). "Of these, the PPM1D and PIGN genes have previously been identified as markers of colorectal cancer with a poor prognosis when highly expressed, whereas PLK2 has been described as a gene that promotes tumor growth in colorectal cancer." (PMID 35682850, 2022). "One study showed that PLK2 promoted colorectal cancer growth and inhibited apoptosis by targeting Fbxw7/Cyclin E." (PMID 35156101, 2021). "FOXD1 could be able to promote cell proliferation and inhibit apoptosis by regulating polo-like kinase 2 in colorectal cancer." (PMID 40173324, 2025). "Contradictory effects of PLK2 in colorectal cancer also have been reported." (PMID 35156101, 2021). "In addition, a recent study reported that high PLK2 expression correlated with poor outcomes in colorectal cancer (CRC) and served as a prognostic biomarker." (PMID 32878237, 2020). "In addition, using both FOXD1 and Plk2 may as a novel biomarker can better predict poor prognosis in colorectal cancer." (PMID 38827805, 2024).
breast carcinoma (11 papers, 2013 to 2025). "Paradoxically, frequent loss of chromosome 5q11–35, which includes PLK2, is observed in basal-like breast cancer." (PMID 35156101, 2021). "Therefore, it is conceivable that PLK2 is tumor suppressive in breast cancer, specifically that chromosomal loss of PLK2 is highly enriched within the basal-like/triple-negative subtypes of breast cancer." (PMID 35156101, 2021). "PLK2 was shown to be a tumor suppressor in breast cancer (basal-like and triple-negative breast cancer subtypes) and loss of PLK1 rescued phenotypes after PLK2 knockdown in vitro and in vivo." (PMID 40379873, 2025). "RP-7 downregulated prognostic markers (epidermal growth factor-like protein 8) and upregulated tumor suppressor genes (PLK2) in breast cancer cells, along with suppressing SLC39A10 involved in cancer progression." (PMID 38272230, 2024). "Here, we demonstrated that PLK2 functions as a tumor suppressor in breast cancer, and suggested that its tumor-suppressive role is mediated, at least partially, by its direct interaction with PLK1." (PMID 35156101, 2021). "This paradox stimulated us to investigate the functions of PLK1 and PLK2 in breast cancer, as well as potential translational implications." (PMID 35156101, 2021). "In this study, we found that PLK2 was tumor suppressive in breast cancer, preferentially in basal-like and triple-negative breast cancer (TNBC) subtypes." (PMID 35156101, 2021). "To gain more insight into the CNAs in different breast cancer subtypes, we performed GISTIC analysis on TCGA breast tumors and discovered that the loss of PLK2 was identified in 21.8% of all patients with breast cancer." (PMID 35156101, 2021). "Including Nigerian samples along with TCGA allowed us to identify PLK2, KDM6A, and B2M as novel significantly mutated genes in breast cancer, with the former two enriched in the HER2 + subtype." (PMID 30327465, 2018). "PLK2, KDM6A, and B2M are also identified as previously unreported significantly mutated genes in breast cancer." (PMID 30327465, 2018). "In some studies, however, PLK2 promotes the cell proliferation in the SKBR3 cells (breast cancer) and primary keratinocyte, respectively, which suggests that the gene plays an oncogenic role." (PMID 25239093, 2014). "We identified six PDX models from the Baylor College of Medicine breast cancer PDX collection according to their PLK2 mRNA expression and known response to carboplatin from an ongoing preclinical trial, and tested the efficacy of volasertib in combination with carboplatin." (PMID 35156101, 2021). "Surprisingly, almost none of the existing established human breast cancer cell lines exhibited a loss of PLK2 (see Discussion)." (PMID 35156101, 2021). "Furthermore, PLK2 mRNA expression is significantly lower in breast cancer as reported in the TCGA dataset." (PMID 35156101, 2021). "The apparent paradox that PLK1 and PLK2 might exert opposite roles in breast cancer led us to study potential links between PLK2 and PLK1." (PMID 35156101, 2021). "Specifically, in breast cancer, emerging biomarkers such as polo-like kinase (PLK) PLK 2, PLK3, and PLK5 have been validated as significant prognostic indicators through survival analysis utilizing the Kaplan–Meier Plotter database." (PMID 39432619, 2024). "When breast cancer cell line MCF-7 is exposed to zinc, expression of PLK2 is dramatically reduced, leading to cell cycle arrest and cancer cell adaption." (PMID 35898867, 2022).
breast carcinoma (continued). "We then examined mRNA expression in the TCGA database to further investigate the relationship between PLK2 and PLK1 in breast cancer." (PMID 35156101, 2021). "Although PLK2 belongs to the same family as PLK1, and both kinases are implicated in cell-cycle progression, recent studies as well as our data presented herein suggest that PLK2 may actually be a tumor suppressor that is silenced in many types of cancers, including breast cancer." (PMID 35156101, 2021).
Parkinson disease (11 papers, 2014 to 2025). A progressive degenerative disorder of the central nervous system characterized by loss of dopamine producing neurons in the substantia nigra and the presence of Lewy bodies in the substantia nigra and locus coeruleus. "Recently, a new degradation route of α-synuclein (a protein strongly linked to the pathogenesis of Parkinson’s disease) by PLK2 has been described, offering new opportunities for the development of therapeutic strategies." (PMID 31756991, 2019). "Beyond cancer, PLK2 and PLK3 have received attention in neurodegenerative diseases, because phosphorylation of synuclein at Ser129 is a hallmark of Parkinson disease and related synucleinopathies." (PMID 40379873, 2025). "Modulating the activity of the PLK2 gene has been proposed as a therapeutic strategy for the treatment of Parkinson’s disease." (PMID 36845551, 2023). "R78 drug molecule has shown potent results as an inhibitor for PLK2 protein for Parkinson's disease treatment." (PMID 36484071, 2022). "Although the pathophysiology of the Ser-129 phosphorylation in Parkinson's disease is not completely understood and it has not been clarified whether this phosphorylation is protective or harmful for neurons, PLK2 is considered a very promising target for Parkinson disease treatment." (PMID 25338102, 2014). "This is consistent with neuroprotection research: in Parkinson’s models, PCA mediates p-GSK3β phosphorylation through PLK2, blocking its degradation of Nrf2." (PMID 41306290, 2025). "An alternative pathway for inhibiting GSK-3β is phosphorylation by the polo-like kinase 2 (PLK2) at Point 40, which is upregulated by protocatechuic aldehyde—an Nrf2 activator shown to ameliorate symptoms in models of Parkinson’s disease." (PMID 36829925, 2023). "Polo-like kinase 2 (PLK2) has been recently recognized as the major enzyme responsible for phosphorylation of α-synuclein at S129 in vitro and in vivo, suggesting that this kinase may play a key role in the pathogenesis of Parkinson's disease and other synucleinopathies." (PMID 25338102, 2014). "The human acetylcholine esterase (AChE, PDB ID: 4M0E), monoamine oxidase B (MAO-B; PDB ID: 6FVZ), and Polo-like kinase-2 (PLK2; PDB ID: 4I5P) were selected as three possible pharmacological target proteins for IR3G and IR in the pathway of neuroprotective and anti-Parkinson’s activities." (PMID 35270118, 2022).
osteosarcoma (10 papers, 2014 to 2026). A usually aggressive malignant bone-forming mesenchymal neoplasm, predominantly affecting adolescents and young adults. "siRNA-silencing of PLK2 gene promoted apoptosis during mitosis in various cancer cell lines (e.g., carcinoma of lung, cervix, breast and colon, and osteosarcoma) in the presence of spindle poisons like paclitaxel." (PMID 34065956, 2021). "Taken together, the present study indicated that circ_0102049 suppressed the progression of osteosarcoma via modulating miR-520g-3p/PLK2/TAp73 axis, providing a potential therapeutic target for OS." (PMID 34060415, 2021). "And miR-126 is likely a promotor of apoptotic cell death in osteosarcoma cells by regulation of PLK2, PI3KR2, Crk, PI3K, Akt, and so on." (PMID 25510179, 2014). "In colorectal carcinomas, PLK2 exerts tumor growth-promoting and apoptosis-inhibiting effects as is the case for several other tumors like lung cancer, cholangiocarcinoma, osteosarcoma, and head and neck carcinoma." (PMID 34065956, 2021). "Circ_0102049 could heighten PLK2 expression by depressing miR-520g-3p, and inhibit proliferation, invasion, migration and cell cycle of osteosarcoma (OS) cell line MG63; PLK2 inhibiting leads to a significant elevation in tumor volume and weight in the MG63 cell xenograft mouse model." (PMID 35898867, 2022).